AXDND1 (axonemal dynein light chain domain containing 1)
Description:
May be essential for spermiogenesis and male fertility probably by regulating the manchette dynamics, spermatid head shaping and sperm flagellum assembly.
Synonyms: C1orf125; FLJ32940
Tractability: No criterion of Open Targets' tractability assessment is met for any kind of drug.
Gene: Protein-coding gene on chromosome 1 (179,365,720 to 179,554,735, forward strand). Ensembl gene ENSG00000162779.
Subcellular location: Cytoplasm
Subcellular location (Human Protein Atlas): Cytosol; Primary cilium; Basal body
Gene Ontology:
Biological process: manchette assembly; spermatogenesis
Cellular component: cytoplasm; cytosol
Genetic constraint (gnomAD): Loss-of-function variants: 74 observed, 91.56 expected, observed/expected ratio (o/e) 0.81, 90% interval 0.67 to 0.98. The upper end of that interval is the gene's LOEUF score, 0.98, which puts it in group 4 of 6, group 1 being the genes least tolerant of losing a copy. Missense variants: 961 observed, 971.13 expected, observed/expected ratio (o/e) 0.99, 90% interval 0.94 to 1.04. Synonymous variants: 334 observed, 335.18 expected, observed/expected ratio (o/e) 1, 90% interval 0.91 to 1.09.
Homologues: Orthologues: chimpanzee AXDND1 (99% identical), macaque AXDND1 (91% identical), dog AXDND1 (76% identical), pig AXDND1 (75% identical), rabbit AXDND1 (74% identical), rat Axdnd1 (65% identical), mouse Axdnd1 (65% identical), tropical clawed frog axdnd1 (33% identical), zebrafish axdnd1 (32% identical).
Diseases named in the same sentence as AXDND1 in open-access papers:
AXDND1 is named in the same sentence as 8 diseases in open-access papers, as found by Europe PMC text mining. Sharing a sentence is not in itself a finding about the gene and the disease. The quoted sentences say what the papers report.
Azoospermia (2 papers, 2021 to 2024). Absence of any measurable level of sperm,whereby spermatozoa cannot be observed even after centrifugation of the semen pellet. "We aimed to test if AXDND1 was a human male infertility gene and validate its link to azoospermia in the infertile men containing AXDND1 variants." (PMID 38997255, 2024). "We identified two potentially deleterious mutations of AXDND1 unique to non‐obstructive azoospermia (NOA) patients through selected exonic sequencing." (PMID 34759295, 2021). "Two potentially deleterious heterozygous mutations of AXDND1 unique to non‐obstructive azoospermia (NOA) patients were found through selected exonic sequencing." (PMID 34759295, 2021). "To determine whether AXDND1 is associated with clinical azoospermia, we conducted a large-scale exonic sequence analysis of the AXDND1 gene from our previous published data containing 757 NOA patients and 706 fertile men." (PMID 34759295, 2021). "In support of their potential pathogenicity, however, the clinical presentation of both men was azoospermia, which is a match with patient 1 and the Axdnd1 knockout mouse." (PMID 38997255, 2024). "Previously we used whole exome sequencing on a group of infertile men with azoospermia (no sperm in their ejaculate) and identified a novel biallelic stop-gain variant in the dynein-related gene AXDND1." (PMID 38997255, 2024). "Finally, we identified an additional four potentially compound heterozygous biallelic variants of unknown significance in AXDND1, in men suffering non-obstructive azoospermia suggesting that the insights into the function of AXDND1 in the mouse apply to humans." (PMID 38997255, 2024).
male infertility (2 papers, 2021 to 2024). The inability of the male to effect fertilization of an ovum after a specified period of unprotected intercourse. "Previously it has been shown that the loss of Axdnd1 function in mice results in male infertility due to its role in sperm head shaping via the manchette and tail assembly during spermiogenesis." (PMID 38997255, 2024). "Further in vivo loss of function study showed that Axdnd1 gene knockout in mice resulted in progressive germ cell loss, deformed sperm head and/or flagellum structures during the last stage of spermatogenesis, thereby causing male infertility." (PMID 34759295, 2021).
nephrotic syndrome (1 paper, 2023). A collection of symptoms that include severe edema, proteinuria, and hypoalbuminemia; it is indicative of renal dysfunction. "Group 1 was characterized by major risk genes for developing LOAD (APOC1 and APOC1P1) and immune-related genes (RELB and CBLC), whereas group 2 was characterized by genes associated with kidney disorders, such as nephrotic syndrome (AXDND1, FBP1, and MIR2278)." (PMID 37386009, 2023). "Several variants in AXDND1 have been registered as mutations involved in nephrotic syndrome in the GeneCards and ClinVar databases." (PMID 37386009, 2023).
oligoasthenoteratozoospermia (1 paper, 2021). A form of male infertility that is characterized by a combination of low number or oligozoospermia, poor motility or asthenozoospermia, and abnormal shape or teratozoospermia of sperms. "Importantly, Axdnd1 knockout males are sterile with reduced testis size caused by increased germ cell apoptosis and sloughing, exhibiting phenotypes consistent with oligoasthenoteratozoospermia." (PMID 34759295, 2021).
cancer (1 paper, 2025). A tumor composed of atypical neoplastic, often pleomorphic cells that invade other tissues. "In contrast, AXDND1 remains largely unexplored in cancer biology." (PMID 41395597, 2025).
kidney diseases (1 paper, 2023). "The other was characterized by genes associated with kidney disorders (AXDND1, FBP1, and MIR2278)." (PMID 37386009, 2023). "On the other hand, three of the four representative genes in group 2 (AXDND1, FBP1, and MIR2278) are likely to be associated with kidney diseases." (PMID 37386009, 2023).
AXDND1 also shares sentences with these, for which no sentence is quoted: Hypertension (1 paper); infertile (1).